RNU6-29P (RNA, U6 small nuclear 29, pseudogene)
Synonyms: RNU6-29
Gene: Small nuclear RNA gene on chromosome X (48,776,965 to 48,777,071, reverse strand). Ensembl gene ENSG00000207367.
Homologues: Orthologues: guinea pig U6 (96% identical), pig U6 (93% identical), dog U6 (89% identical). Paralogues in human: RNU6-25P (98% identical), RNU6-1 (97% identical), RNU6-2 (97% identical), RNU6-39P (97% identical), RNU6-3P (97% identical), RNU6-4P (97% identical), RNU6-5P (97% identical), RNU6-6P (97% identical), RNU6-9 (97% identical), RNU6-12P (96% identical), RNU6-13P (96% identical), RNU6-16P (96% identical), and 1287 more.